RET (ret proto-oncogene)
Diseases named in the same sentence as RET in open-access papers (continued):
Sharing a sentence is not in itself a finding about the gene and the disease.
thyroid cancer (continued). "PCCL3 cells also have been used to create cell culture models of thyroid carcinomas caused by oncogenic driver mutations in BRAF and RAS, and RET gene fusions." (PMID 26595524, 2015). "The majority of thyroid carcinomas contain one of a small number of driver mutations, such as BRAF or RAS mutations, gene fusions involving RET, or gene fusions between PAX8 and PPARG." (PMID 26595524, 2015). "PP2 reduced RET/PTC1-mediated MAPK signaling and inhibited the invasive phenotype and the proliferation of human thyroid carcinoma cells with RET/PTC1 rearrangements." (PMID 26635725, 2015). "A transmodulation between PLD2 and the oncogenic kinase RET is evident in thyroid cancer cells where PLD2 enhances STAT3 phosphorylation and transcriptional activation that is mediated by RET." (PMID 24103483, 2014). "In addition, the activity of lenvatinib through the inhibition of multiple RTKs may contribute to its antitumor activity against thyroid cancer cell lines with gene alterations (e.g., mutations or rearrangements) and overexpression of targeted RTKs, such as RET and FGFR1." (PMID 25295214, 2014). "While activating mutations of BRAF, RAS genes and RET/PTC gene rearrangements promote PTC, other genetic and epigenetic modifications that contribute to malignant progression of this type of thyroid cancer are insufficiently defined." (PMID 25490036, 2014). "RET/PTC3 has been found to be more frequent than RET/PTC1 in cases of thyroid cancers exposed to post-Chernobyl radiations, mostly found in young subjects and is usually associated with an aggressive phenotype, a short latency period and poor prognosis." (PMID 24759995, 2014). "In conclusion, the significance of siRNA RET/PTC3-SQ NPs have been demonstrated in preclinical studies for thyroid cancer therapy and further pharmacological and clinical investigations can be proceeded to set-in the remedy of thyroid carcinoma." (PMID 24759995, 2014). "Numerous studies have identified RET as a potentially important therapeutic target in subtypes of breast, lung and thyroid cancers." (PMID 25409876, 2014). "Without a US FDA-approved RET CDx, not only will potential RET inhibitors not gain US FDA approval to treat RET-rearranged NSCLC but other RET-rearranged malignancies such as thyroid cancer or chronic myelomonocytic leukemia (CMML)." (PMID 24744988, 2014). "The RET/PTC3 rearrangement is associated with an aggressive form of PTC and was observed in the thyroid cancers at contaminated areas after Chernobyl explosion." (PMID 24759995, 2014). "We investigated the effect of SPP86 on ERK1/2 phosphorylation in thyroid cancer derived cell lines expressing the RET/PTC1 rearrangement (TPC1), BRAFV600E (8505C) or RASG13R (C643) mutations." (PMID 25409876, 2014). "Recently, the efficacy of the JAK1/2 inhibitor AZD1480 against the growth of thyroid cancer was tested in vitro and in vivo in thyroid cancer cell lines that expressed oncogenic RET." (PMID 23509459, 2013). "Fragile site breakage was previously shown to result in rearrangement of the RET oncogene, resembling the rearrangements found in thyroid cancer." (PMID 24040417, 2013). "Our data provide new mechanistic insights regarding how fragile site breakage at the RET oncogene can lead to generation of carcinogenic rearrangements found in thyroid cancer." (PMID 24040417, 2013). "There have been several genetic abnormalities associated with thyroid carcinoma including point mutations such as those in the RAS and BRAF genes, and chromosomal rearrangements such as RET/PTC and PAX8/PPARγ." (PMID 23717622, 2013). "We demonstrated that AZD1480 directly inhibits the kinase activity of recombinant RET in a dose-dependent manner, which likely underlines the inhibitory and mutant-RET specific effects of AZD1480 on the growth and survival of thyroid cancer cells." (PMID 23056499, 2012).
thyroid cancer (continued). "Here, we tested the efficacy of a JAK1/2- inhibitor, AZD1480, in the in vitro and in vivo growth of thyroid cancer cell lines expressing oncogenic RET." (PMID 23056499, 2012). "Herein, we investigated the biological effects of a JAK1/2 inhibitor, AZD1480, on the growth of PTC- and MTC- derived thyroid cancer cell lines harboring activating RET/PTC rearrangements and RET mutations, respectively." (PMID 23056499, 2012). "RET gene alterations are oncogenic “drivers” in thyroid cancer pathogenesis, particularly in MTC and PTC." (PMID 23056499, 2012). "In this study, we determined the sensitivity of thyroid cancer cell lines harboring oncogenic forms of RET to JAK1/2 inhibitor, AZD1480." (PMID 23056499, 2012). "Thyroid cancer cell lines harboring RET/PTC1 (TPC-1), RET M918T (MZ-CRC1) and RET C634W (TT) alterations, as well as TPC-1 xenografts, were treated with JAK inhibitor, AZD1480." (PMID 23056499, 2012). "In conclusion, we showed that the JAK1/2 inhibitor, AZD1480, can block the growth and induce cell death of thyroid cancer cell lines harboring distinct forms of oncogenic RET in vitro and in vivo." (PMID 23056499, 2012). "Furthermore, AZD1480 potently inhibited the in vivo growth of TPC-1 xenografts, resulting in tumor regression, while the tumors from AZD6244- treated mice grew slightly more than the control tumors, suggesting that treating RET-mutated thyroid cancers with this inhibitor may promote tumor growth." (PMID 23056499, 2012). "Many studies have examined use of other molecular markers including RAS, RET/PTC rearrangement, and/or PAX8/PPARγ rearrangement to improve the diagnostic accuracy of thyroid carcinomas." (PMID 23049733, 2012). "Regarding specific mutations that constituted the panel for thyroid cancer diagnostic, RAS, BRAF, RET/PTC, and PAX8/PPARγ mutations had all a 100% positive predictive value for cancer." (PMID 22654559, 2011). "Further, XB130 binds the p85α subunit of phosphatidyl-inositol-3-kinase and subsequently mediates signaling through RET/PTC in thyroid cancer cells." (PMID 21884627, 2011). "The genes, coding the signaling cascade proteins (RET, RAS, BRAF, PI3K, PTEN, AKT), are mutated or aberrantly expressed in thyroid cancer derived from follicular thyroid cell." (PMID 22654559, 2011). "Mutations in RET in medullary, papillary and familial thyroid carcinoma make RET another promising target for the treatment of thyroid cancer." (PMID 22654559, 2011). "In thyroid carcinomas, the proto-oncogenes RET and NTRK1 are often found to be activated through chromosomal rearrangements." (PMID 22096618, 2011). "Microarray analyses of 24 thyroid carcinomas – 7 classic papillary, 8 follicular variants of papillary (fvPTC), 4 follicular (FTC) and 5 PDTC – were performed and correlated with RAS, BRAF, RET/PTC and PAX8-PPARG alterations." (PMID 19809427, 2009). "RET is a well-known oncogene that plays a role in the development of thyroid carcinomas and the familial cancer syndrome multiple endocrine neoplasia." (PMID 18840272, 2008). "The importance of this pathway has been well established in thyroid cancer, where in PTCs the MAPK pathway is driven by the activation of point mutations of the BRAF and RAS genes and in the RET/PTC rearrangement, these genetic alterations being found in more than 70% of PTCs." (PMID 40722651, 2025). "RET-altered thyroid cancers demonstrate responsiveness to selective RET inhibitors." (PMID 41515542, 2025). "RET was not correlated in thyroid cancer but was positively associated in prostate and head and neck cancers." (PMID 40548474, 2025). "However, in the context of thyroid cancer, a notable exception emerges, as numerous samples manifest an elevated expression of wild-type RET." (PMID 41373459, 2025).
thyroid cancer (continued). "Combining both fusion partner and intragenic fusions, we identified a total of 10 RET+ CRC patients out of 14,812 CRC patients (0.07%), 109 RET+ NSCLC patients out of 21,397 NSCLC patients (0.5%), and 75 RET+ thyroid cancer patients out of 1944 non‐medullary thyroid cancer patients (3.9%)." (PMID 39950716, 2025). "Furthermore, genomic-based targeted therapies have been developed for NTRK and RET gene fusion-positive DTCs, emphasizing the importance of molecular profiling in guiding treatment decisions for patients with thyroid cancer." (PMID 39744583, 2025). "In order to assess the accuracy of these predictions, a total of 11 thyroid cancer samples with p < 0.01—including the four cases with predicted RET fusions—were subjected to further experimental validation using the targeted NGS panel OncoFu and Sanger sequencing." (PMID 41373459, 2025). "In this study, we found that pralsetinib, a selective RET inhibitor approved for the treatment of RET fusion–positive non-small cell lung cancer and thyroid cancer, exhibits potent anti-tumor activity against TMZ-resistant glioma cells both in vitro and in vivo." (PMID 41244832, 2025). "RET inhibitors are another kind of targeted therapeutic agent that could be beneficial for RET‐altered thyroid cancers, such as ATC." (PMID 40309640, 2025). "It has been proposed that HT may induce RET rearrangement, essentially turning it into a gene for thyroid cancer, due to the body's immune response to thyroid cancer antigens." (PMID 40269951, 2025). "For radioactive iodine-refractory (RAIR) differentiated thyroid cancer, tissue-based biomarker testing to identify actionable alterations (NTRK1/3 fusions, RET fusions, and BRAF V600E mutations) is recommended, with moderate certainty evidence from the American Thyroid Association." (PMID 41595456, 2025). "Studies have also shown efficacy for both medications in RET-altered thyroid cancer." (PMID 40332427, 2025). "Univariate binary logistic regression analysis identified age, T stage, N stage, unilateral thyroid involvement, maximum tumor diameter, extra-glandular invasion, and RET, TERT, and BRAF gene mutations as factors significantly associated with lung metastasis in thyroid cancer." (PMID 41306438, 2025). "Therefore, future strategies should prioritize the development of next-generation inhibitors and the optimization of combination regimens to improve outcomes for RET-altered thyroid cancer patients." (PMID 41278287, 2025). "Selective RET inhibitors as selpercatinib and pralsetinib have shown high response rates and improved tolerability in RET-mutated thyroid cancers, while larotrectinib and entrectinib target NTRK fusions across tumor types, including rare thyroid cancer subtypes." (PMID 41463055, 2025). "PTC in SO shares mutations like BRAF, RET, and RAS with primary thyroid cancers." (PMID 39963400, 2025). "Additionally, the single poorly differentiated thyroid carcinoma case also harbored a RET translocation; making RET rearrangements present in a total of 7/58 tumors of the thyroid gland." (PMID 40338900, 2025). "This is amplified by the fact that the fusion proteins originating from the majority of the detected driver mutations, namely those of RET, NTRK3, CCDC6 (when co-occurs with RET), and MET, can be effectively targeted with small tyrosine kinase inhibitors in thyroid cancer." (PMID 39409115, 2024). "Selpercatinib is a selective RET inhibitor that is currently FDA approved in patients with advanced medullary thyroid carcinoma and RET mutations and in RET fusion-driven thyroid cancer regardless of histology." (PMID 38438731, 2024). "Thyroid cancer is found closely related to the activation of RET." (PMID 37874339, 2024). "We treated two patients with RET-mutant thyroid cancer with a selpercatinib and MitoQ combination." (PMID 38378752, 2024).
thyroid cancer (continued). "The differential effects of formalin fixation on DNA and RNA quality present a challenge in optimizing sample preparation for thyroid cancer genomic analysis, where both DNA-based (e.g., BRAF V600E mutations) and RNA-based (e.g., RET and NTRK fusion genes) analyses are crucial." (PMID 39560912, 2024). "Similarly, 19 patients with RET fusion-positive thyroid cancers demonstrated an impressive response rate of 79% (95% CI 54–94)." (PMID 39061168, 2024). "In differentiated thyroid cancers such as PTC and FTC, a limited number of mutations such as BRAF p.V600E, RET translocations (CCDC6::RET, NCOA4::RET, etc.), H/K/NRAS mutations such as NRAS p.Q61R, and PAX8::PPARG translocation are often found, and these are mutually exclusive." (PMID 38672067, 2024). "The RET/papillary thyroid carcinoma 1 (PTC1) oncogene, frequently found in human papillary thyroid carcinomas, involves the fusion of RET’s kinase domain with the initial 101 amino acids of CCDC6, leading to allelic expression loss and influencing thyroid cancer development." (PMID 39457720, 2024). "Based on a pooled popPK analysis that included data from patients with RET-altered thyroid cancers, patients with RET-fusion NSCLC and healthy subjects in different pralsetinib studies, disease status does not have a clinically relevant impact on the PK of pralsetinib." (PMID 38675225, 2024). "At present, several clinical trials of selpercatinib for RET-altered thyroid cancer are still ongoing, including the study of whether selpercatinib can increase the uptake of RAI in RET-altered RAI-RTC." (PMID 39473507, 2024). "Genetic testing associated with thyroid cancer was performed and did not reveal any of the known mutations, such as RET gene mutation for MEN2A, MEN2B, or familial MTC." (PMID 39650941, 2024). "Furthermore, some reports have suggested that thyroid carcinomas with the RET and/or NTRK fusion genes tend to be aggressive; our findings indicate a more complex scenario." (PMID 38472412, 2024). "Nevertheless, the negative immunoreactivity for BRAF V600E in all cases indicates that the combination of morphological analysis with immunohistochemistry may improve the prediction for thyroid carcinoma harboring the RET and/or NTRK fusion genes." (PMID 38472412, 2024). "The prognosis of patients with metastatic RET-altered thyroid cancer is poor." (PMID 37207147, 2023). "Nevertheless, combination therapy might prove to be the most effective strategy for patients with RET-driven advanced thyroid cancer." (PMID 37207147, 2023). "This review provides a perspective on the clinical benefit of such targeted therapies in advanced thyroid cancer to date, with a focus on the present clinical management of RET-driven advanced thyroid cancer in Europe and the landscape of prospective advancements." (PMID 37207147, 2023). "These RET-selective inhibitors have demonstrated potent efficacy and favourable toxicity profiles in clinical trials and are now a new therapeutic option for patients with RET-altered thyroid cancers in the clinical setting." (PMID 37207147, 2023). "Environmental and genetic factors play important roles in the pathogenesis of thyroid cancer, and genetic changes, such as BRAF and RAS mutations or RET/PTC rearrangement leading to activation of the oncogenic MAPK pathway, are closely related to the occurrence of thyroid cancer." (PMID 36791151, 2023). "The ARROW trial also included a cohort of RET-mutant MTC and RET fusion–positive thyroid cancers." (PMID 38201460, 2023). "Timing and process for testing for RET alterations may also differ depending on the type of thyroid cancer." (PMID 37277734, 2023). "In addition to RET fusion-positive thyroid cancers, selpercatinib was also demonstrated durable and robust responses in RET fusion-positive NSCLC and 12 other types of solid tumor." (PMID 37081420, 2023).
thyroid cancer (continued). "Examples include February 4, 2020 (World Cancer Day), May 8, 2020 (United States Food and Drug Administration approval of Selpercatinib for advanced RET-driven lung and thyroid cancers), and September 1, 2020 (the first day of Thyroid Cancer Awareness Month)." (PMID 37531163, 2023). "Importantly, the optimal benefits of available specific targeted treatments for advanced RET-driven thyroid cancer require genetic testing." (PMID 37207147, 2023). "Overall, selpercatinib was well tolerated with durable efficacy, and subsequently received accelerated approval based on these initial data from the first 144 NSCLC patients, 143 MTC patients and 19 RET fusion–positive thyroid cancer patients in the LIBRETTO-001 trial." (PMID 38201460, 2023). "This article reports on the findings related to the following objective: to assess clinical practice gaps and challenges experienced by pathologists involved in RET-altered lung and thyroid cancer care in Germany, Japan, the United Kingdom, and the United States." (PMID 37277734, 2023). "The frequency of CCDC6::RET in sporadic thyroid cancer is higher than that of NCOA4::RET." (PMID 37188126, 2023). "More RET-specific or selective RET inhibitors (SRIs; selpercatinib and pralsetinib) were developed and were subsequently approved and are now established as standard of care treatment across a variety of indications including lung and thyroid cancer." (PMID 38201460, 2023). "No RET fusion genes were identified in other types of thyroid carcinomas, MTCs, FTCs, ATCs, PDTCs, OCAs, or in any low-risk neoplasms or benign thyroid lesions." (PMID 37882481, 2023). "While selective RET inhibitors show potent activity in brain metastases of lung and thyroid cancer patients, the emergence of therapeutic resistance to RET inhibitors suggests activation of additional or alternative pathways that circumvent pharmacological inhibition of RET." (PMID 35957881, 2022). "LIBRETTO-001 clinical trial (ClinicalTrials.gov, Identifier NCT03157128) enrolled 531 patients of whom 162 with RET-mutant thyroid cancers, between May 2017 and June 2019." (PMID 35422765, 2022). "ORR rate was similar (79%) also in the remaining patients with RET fusion-positive thyroid cancers." (PMID 35422765, 2022). "In addition to lung cancers, RET fusions were also frequently detected in colorectal and thyroid cancers." (PMID 36369474, 2022). "In addition, the proliferation rate of thyroid cancer cells with RET kinase mutations has been shown to be inhibited by AST-487 treatment, which is interesting since thyroid cancer has a high rate of hTERT promoter mutations." (PMID 36142729, 2022). "Lately, a more personalized approach in the management of advanced thyroid cancer patients has improved the outcomes, and several novel molecularly guided therapies, including selective RET inhibitors (sRETis), have demonstrated promising efficacy in clinical trials." (PMID 35884466, 2022). "Collectively, these results indicate that key mechanisms of primary and acquired resistance to selective RET inhibitor therapy in RET-altered lung and thyroid cancers converge on MAPK pathway activation, with diverse yet partially overlapping and often co-existent mechanisms in individual patients." (PMID 35304457, 2022). "Additionally, mutations that trigger RET activity led to multiple endocrine neoplasia type 2A and 2B (MEN2A and MEN2B) and familial medullary thyroid carcinoma (FMTC) thyroid cancers." (PMID 36003330, 2022). "Our data suggest that SHP2 may play a unique role in modulating ERK pathway activation in CCDC6-RET–rearranged thyroid cancer cells, and that pSHP2 and pSTAT3 may be biomarkers of adaptive resistance to RET inhibition." (PMID 35510953, 2022).